MTOR (mechanistic target of rapamycin kinase)
Diseases named in the same sentence as MTOR in open-access papers (continued):
Sharing a sentence is not in itself a finding about the gene and the disease.
tumor (continued). "Beyond its approved applications, sirolimus has been extensively investigated for its potential anticancer activity, as mTOR dysregulation is a hallmark in many tumor types, including lung cancer." (PMID 41304874, 2025). "Compound 23 inhibits both C1 and C2 complexes of mTOR and causes tumor regression in a study with mouse xenograft models." (PMID 38584538, 2025). "It further induces autophagy-associated cell death in HL-60 cells via the CaMKKβ/AMPK/mTOR signaling pathway and exhibits other anti-tumor effects as well." (PMID 39275063, 2024). "Activation of the PI3K/AKT/mTOR pathway has long been associated with resistance to multiple targeted therapies across multiple tumor types, leading to the evaluation of combination therapies integrating inhibitors of this pathway." (PMID 38672538, 2024). "The PIK3CA is a tumour-specific gene that encodes type IA P13K protein to activate the P13K/Akt/mTOR signalling pathway in promoting cell proliferation." (PMID 38245692, 2024). "As we all know, PI3K/Akt/mTOR signaling is one of the most frequently dysregulated signaling cascades in human malignancies and is implicated in a wide variety of different neoplasms." (PMID 38341472, 2024). "Tumor cells and tumor‐associated macrophages (TAMs) that highly express PD‐L1 can impair the PI3K/AKT/mTOR pathway, directly affecting glycolysis." (PMID 39492834, 2024). "AMPK can inhibit mTOR signaling through direct phosphorylation of TSC2 (the tumor suppressor) and Raptor (a protein associated with mTOR regulation)." (PMID 39268468, 2024). "mTOR inhibitors are also effective in tumor types associated with RAS dysregulation; however, feedback signaling mediated by S6 kinase can increase AKT signaling, bypassing the inhibitory effects of the mTOR inhibitor." (PMID 39016685, 2024). "Studies have reported that SPP1 can activate the PI3K/AKT/mTOR signaling pathway through PKCα phosphorylation, a pathway closely associated with tumor invasion and metastasis." (PMID 39066845, 2024). "Although selective inhibitors of Rictor and the Rictor-mTOR association are only in a preclinical phase, they seem to be potent novel approaches to reduce tumor cell migration and metastasis formation." (PMID 38339294, 2024). "Compound 4o, in particular, exhibited promising activity by targeting the PI3K/Akt/mTOR signaling pathway, inhibiting tumor survival, inducing apoptosis, and causing cell cycle arrest in MCF-7 cell lines." (PMID 38773663, 2024). "The sustained activation of AKT leading to Merlin repression and mTOR exploitation in PMe has been linked to calretinin (CR), which is overexpressed in certain types of tumours and pathologies, including colon carcinoma and PMe." (PMID 38459714, 2024). "AKT1, a serine/threonine kinase, is a crucial component of the PI3K/Akt/mTOR pathway that enhances tumor formation, and its overexpression is linked to a bad outcome in GBM patients." (PMID 39092253, 2024). "Paired immortalized mouse embryonic fibroblast (MEF) cell lines deficient of these tumor suppressors have been widely used as mTOR activation model cell lines." (PMID 39333852, 2024). "Increased glutamine synthesis or utilisation impacts tumour epigenetics, oxidative stress, autophagy, immunity and associated pathways, such as the mTOR (mammalian target of rapamycin) pathway." (PMID 38699532, 2024). "It is appealing to associate the role of autophagy in late-stage tumours to the role of mammalian target of rapamycin (mTOR)." (PMID 38794172, 2024). "For the underlying mechanism, we proposed that the PI3K/AKT/mTOR pathway is the key process for the role of DCLK1 in tumor progression and the occurrence of the EMT program." (PMID 38980538, 2024). "The mTOR pathway and its regulators are significantly linked to PTs invasion, staging, and tumor growth, and provide important predictive and prognostic value for PTs patients." (PMID 39736867, 2024).
tumor (continued). "MTOR is frequently abnormally activated in tumors, and the PI3K/Akt signaling pathway, which is upstream of mTOR, is also implicated in tumor development." (PMID 39598398, 2024). "The FoxO signaling pathway, which was identified here with a predicted FDR very similar to that of mTOR, has also been associated with chemoresistance in a variety of tumor entities." (PMID 39766892, 2024). "Mutations in the phosphatidylinositol 3-kinase (PI3K)/protein kinase B (AKT)/mammalian target of the rapamycin (mTOR) pathway are common in BC (20–40%) and are critical causes of aggressive tumor behavior and therapy resistance." (PMID 38892472, 2024). "Elevated adiposity and altered IGF-1 levels are also linked with OC, where insulin’s tumor-enhancing effects often activate the PI3K/Akt-mTOR pathway, a key regulator of cell growth, proliferation, and survival." (PMID 39596005, 2024). "The PI3K/AKT/mTOR signaling system is linked to other signaling pathways to facilitate tumor growth and metastasis." (PMID 38672455, 2024). "Increased glycolysis in tumor-associated macrophages (TAMs) contributes to tumor angiogenesis, while the inhibition of the mechanistic target of rapamycin (mTOR) suppresses this effect." (PMID 39596288, 2024). "The PI3K/AKT/mTOR signaling pathway is a potent oncogenic hub that is abnormally activated in various tumors and is closely associated with tumor cell survival and proliferation." (PMID 39185308, 2024). "In summary, glutamine deficiency induced by tumor-induced competition highlights the complex role of mTOR in regulating immune cell function." (PMID 38459595, 2024). "Among these miRNA–mRNA pairings, the downregulation of miR-99b-5p and upregulation of MTOR has been implicated as a critical epigenetic event that contributes to tumor aggressiveness in AA PCa and the progression of CRPC." (PMID 38792011, 2024). "Recent research suggests that PI3K/Akt/mTOR induced by glutathione peroxidase 2, which is an antioxidant enzyme associated with tumor metastasis, can upregulate Snail to promote EMT process and metastasis in non‐small cell lung cancer." (PMID 39092293, 2024). "It is notable that the WHO guidelines highlight how MTOR and mTOR pathway mutations can generate a wide variety of histologically diverse tumours as we have observed in this one individual." (PMID 39271965, 2024). "In cases of CoM, an active PI3K/AKT/mTOR pathway has been associated with a higher mitotic index and greater tumor thickness, both indicating poorer prognoses." (PMID 39055896, 2024). "In these studies, tumor invasiveness, metastasis, and poorer prognosis are associated with increased activity of mTOR." (PMID 38515456, 2024). "Substantial evidence has indicated that G0S2 functions as a tumor suppressor by repressing PI3K/Akt/mTOR activity which is associated with Toll-like/MAPK signaling pathways." (PMID 39707168, 2024). "Among the tumor genes, we note some that have been implicated in mTOR activation (MAP2K6 and IL17RC) or inhibition (GJB3) and were upregulated or downregulated, respectively, in everolimus-adapted (LT) tumors." (PMID 39541354, 2024). "The pathogenesis of both is due to the loss of tumor suppression in mitogen-activated protein kinase mammalian target of rapamycin (mTOR) signaling pathways." (PMID 38869960, 2024). "The aberrant PI3K/Akt/mTOR pathway axis is associated with tumorigenesis, tumor progression, and drug resistance." (PMID 38542151, 2024). "The hematoxylin and eosin staining of these tumors showed that mTOR inhibition together with palbociclib caused tumor collapse with smallest residual tumor masses at the end of the treatment." (PMID 38954773, 2024).
tumor (continued). "Compared to monotherapy, JNJ-42756493 (FGFR inhibitor) plus AZD8055 or siolimus (mTOR inhibitor) has a more significant anti-tumor effect in organoids with FGFR3 mutations and nonsense TSC mutations." (PMID 39022082, 2024). "When PTEN is mutated, it affects the PI3K/Akt/mTOR pathway, leading to uncontrolled cell proliferation and tumor cell invasion by blocking apoptosis." (PMID 39057054, 2024). "Increasing evidence has demonstrated that aerobic glycolysis in tumor cells is associated with the AKT/mTOR pathway." (PMID 38890691, 2024). "The detection of both active and inactive mTOR causes confusion in understanding the legitimacy of mTOR suppression in dormant tumor cells." (PMID 38418814, 2024). "Its overexpression is associated with the overactivation of MAPK, JAK/STAT, RAS/MEK/ERK, and PI3K/AKT/mTOR signaling pathways and is associated with the proliferation and differentiation of various tumor cells." (PMID 39247603, 2024). "The overactivation of the PI3K/AKT/mTOR signaling pathway is often found in human tumor tissues and is intimately associated with the generation of tumors." (PMID 38965615, 2024). "In contrast, TMEM127 acts as a tumor suppressor, and loss-of-function mutations have been linked primarily to increased mTOR signaling." (PMID 38687678, 2024). "All four tumours express the mutant MTOR transcript, and an unbiased gene set enrichment test of the tumour transcriptomes revealed the mTORC1 hallmark signalling pathway to be significantly upregulated." (PMID 39271965, 2024). "Often mutated in various cancers, PI3K triggers the PI3K/Akt/mTOR pathway, reducing the effectiveness of T-cell mediated responses by suppressing the activity of tumor-specific T cells and hindering their infiltration into tumors." (PMID 39221221, 2024). "TSC-related gene mutations lead to PI3K/AKT/mTOR pathway dysregulation, promoting benign tumor growth and neurodevelopmental issues." (PMID 39727664, 2024). "Recent findings suggest that the tumor-imposed glycolysis metabolism can restrict T cell functions, dampening the mTOR activity, glycolytic capacity, and IFN-γ production, causing T cell hypo-responsiveness during cancer." (PMID 38254110, 2024). "IGF-1 induces and activates the Ras/Raf/MAPK and PI3K/Akt/mTOR pathways, thereby reducing apoptosis, promoting cell proliferation and survival, and elevating the risk of tumor development." (PMID 39432545, 2024). "This study reported that the inactivation of Tsc1 results in the augmentation of both the frequency and size of tumors, suggesting that Tsc1 functions as a potent tumor-suppressor gene linked to the PI3K/AKT/mTOR pathway in SCLC." (PMID 38473324, 2024). "The direct or indirect inhibition of the PI3K/AKT/mTOR pathway leads to the synthetic lethality of ARID1A-deficient tumour cell clones." (PMID 38893278, 2024). "As a stress-response molecule, AMPK is intricately linked to tumor-suppressive functions through the inhibition of Akt and the downstream mammalian target of rapamycin (mTOR) activity that thereby induces growth suppression and cell cycle arrest." (PMID 38611076, 2024). "In the high writer-score group, heightened activation of the cGMP/PKG and mTOR signaling pathways has been observed, with notable associations to apoptosis and tumor metabolism." (PMID 38291517, 2024). "Aberration of the mTOR pathway occurs in numerous pediatric cancers as a result of gain‐of‐function mutations in oncogenes and/or loss‐of‐function mutations in tumor suppressors, which results in tumor growth, angiogenesis, evading cell death, and metastasis." (PMID 39487711, 2024). "In summary, reduced intra‐tumoral TLS abundance is associated with enhanced mTOR signaling activation and uncontrolled cell cycle progression in tumor cells, and can serve as an indicator of unfavorable prognosis in HCC‐LT." (PMID 38498682, 2024).
tumor (continued). "At the time of trial initiation in 2015, limited clinical data were available regarding the potential to select patients for treatment with PI3K/mTOR/AKT inhibitors based on pathway alterations/mutations in tumor tissue at baseline." (PMID 38539472, 2024). "We also noted that TCRA T-cell fraction was lower in MTOR-mutated tumours (OR = 0.44, 95% CI: 0.2–0.97)." (PMID 39009593, 2024). "Inactivating loss-of-function mutations of the PTEN tumour suppressor gene trigger the over-activation of the mammalian target of rapamycin (mTOR) pathway, which leads to increased cell proliferation, angiogenesis and reduced apoptosis." (PMID 38353885, 2024). "It’s worth noting that P7, with a trunk mutation in TSC2, received the mTOR inhibitor Everolimus after the last progression, associated with tumor regression." (PMID 38448900, 2024). "After tumor mutation analysis, she was eventually treated with an mTOR inhibitor (everolimus), which indicated a phosphatase and tensin homolog (PTEN) mutation." (PMID 39274362, 2024). "Further studies showed that the tumor-promoting effect of DTX3L was associated with the PI3K/AKT/mTOR signaling pathway." (PMID 36614304, 2023). "Recent studies have shown that noncanonical NF-κB signaling is associated with IBN resistance, and PI3K/AKT/mTOR and integrin signaling also confer tumor microenvironment–driven (TME-driven) IBN resistance in MCL." (PMID 36719376, 2023). "Several genomic datasets have illustrated the genomic aberrations of small-bowel adenocarcinoma, and NET presented the frequent mutations, and proposed the effects of mTOR signaling in tumor carcinogenesis." (PMID 36991000, 2023). "TRMT6 non-catalytic subunit is overexpressed and associated with the TNM stage in HCC, through the PI3K/AKT/mTOR axis, and it has been suggested as potential therapeutic target for this tumor type." (PMID 37369946, 2023). "Numerous studies have demonstrated that the abnormal activation of the mTOR pathway through the stimulation of oncogenes or loss of tumor suppressors contributes to tumor growth, angiogenesis, and metastasis." (PMID 36980552, 2023). "The utilization of glucose limits T cells metabolically, causing reduced mTOR activation of T cells and promoting anti-tumor progression." (PMID 36721212, 2023). "Dysregulation of mTOR signaling is frequently associated with tumorigenesis, angiogenesis, tumor growth and metastasis." (PMID 36998461, 2023). "Our previous studies have revealed that the anti-tumour effect of cardamonin is associated with the mTOR signalling pathway." (PMID 37749558, 2023). "MACF1 mutation was also found to upregulate the mTOR signaling pathway and change tumor immune microenvironment." (PMID 37589509, 2023). "The association between the Hh signalling and the PI3K/AKT/mTOR signalling has been found in many tumour entities including oesophageal, ovarian, pancreatic and breast cancers, melanoma, and RMS." (PMID 36765685, 2023). "GSEA identified the tumor hallmark gene sets enriched in the high-risk group, including oocyte meiosis signaling, mTOR signaling pathway, RNA degradation, and cell cycle." (PMID 36597032, 2023). "Firstly, the autophagy signaling pathway for tumor therapy will be reviewed, including oxidative stress, mammalian target of rapamycin (mTOR) signaling and autophagy-associated genes pathway." (PMID 38192627, 2023). "In cell lines of HCC, the knockdown of PIK3R1 significantly reduced the expression of p-PI3K, p-AKT, and p-mTOR, which were closely associated with the growth and proliferation of tumor cells." (PMID 37240068, 2023).
tumor (continued). "Next-generation sequencing identified genetic variations in these tumours, including MTOR gene mutations (4/5) and PIK3CA gene mutation (1/5)." (PMID 36816543, 2023). "In patients receiving dual agent immunosuppression, the regimen that suggested the best balanced tumor response with lower risk of graft rejection or failure was prednisone plus an mTOR inhibitor." (PMID 38993910, 2023). "Reports suggest that PTEN mutation contributes to tumor development, followed by constitutive activation of the p-mTOR pathway." (PMID 37204251, 2023). "Taking these findings together, we propose YC–YR initiation dynamics as a read-out of transcriptional and post-transcriptional mechanisms through which a range of proliferation-associated signaling pathways, including PI3K–Akt–mTOR–Myc, regulate tumor cells." (PMID 37996663, 2023). "Apoptotic cell death can be triggered by inhibition of the mTOR/STAT3 signaling pathways that are closely linked with tumor progression." (PMID 37446140, 2023). "Four tumours had a MTOR gene exon 53 p.L2427Q mutation [c.7280T>A (p.Leu2427Gln)], and one tumour had a PIK3CA gene exon 10 p.E542K mutation [c.1624G>A (p.Glu542Lys)]." (PMID 36816543, 2023). "Overactivation of the PI3K/Akt/mTOR axis in tumor cells can be caused either by genetic mutations or, more frequently, by post-translational modifications." (PMID 37958470, 2023). "Mutations in the RAS-MAPK-ERK and PI3K-Akt-mTOR pathways usually exist in highly differentiated tumor components, and most ATCs are developed from these tumor components." (PMID 37853445, 2023). "We also found MTOR gene mutations in four tumours and an uncommon PIK3CA gene mutation in one tumour in this study." (PMID 36816543, 2023). "In necrotic areas, dying tumor cells release a high number of cations, specifically potassium ions, causing functional starvation of the tumor-infiltrating T cells in parallel to suppression of AKT/mTOR phosphorylation." (PMID 36993986, 2023). "mTOR, a central regulator of multiple tumor-associated signaling pathways, plays important roles in cell proliferation, growth, differentiation, and survival." (PMID 36647780, 2023). "This is in contrast to other tumor types, were rapalog administration results in the acquisition of mTOR resistance mutations." (PMID 37627070, 2023). "In our comprehensive analysis of 57 neoplasms reported in the literature and our series, mTOR gene mutations have been observed in 16 EVTs, 24 LOTs, and 17 RCCs." (PMID 37938323, 2023). "Expression levels of mTOR were significantly higher in TNBC than in HR+ tumors, and high mTOR expression was associated with advanced tumor stage." (PMID 36979714, 2023). "The PI3K/AKT/mTOR signaling pathway is often associated with angiogenesis, making the blockade of this pathway a valuable strategy to inhibit tumor progression." (PMID 38069225, 2023). "BEZ235 is a dual inhibitor of PI3K and mTOR that has been shown to reduce the tumor volume in PCa, which was mediated by the loss of PTEN." (PMID 36900412, 2023). "Loss of activity of this tumor suppressor gene is responsible for upregulation of the PI3K-Akt-mTOR pathway and eventually leads to enhanced cell growth and proliferation." (PMID 38273861, 2023). "A similar decrease in HES1 and mTOR expressions was also observed in tumours derived from ADAM17‐deficient MFE296 cells." (PMID 37165578, 2023). "The in vivo mechanisms of SHR-5’s action are associated with anti-proliferation through the rewiring of tumor cell metabolism via the inhibition of the mTOR pathway." (PMID 37370698, 2023). "Abnormal activation of the mTOR pathway through stimulation of oncogenes or loss of tumor suppressors contributes to tumor growth, angiogenesis, and metastasis." (PMID 37446128, 2023). "Significant enrichment was observed in phagosomes, ABC transporters, and mTOR signaling pathways, which are associated with tumor autophagy, drug resistance, and apoptosis." (PMID 37434634, 2023).